CD4 (CD4 molecule)
Diseases named in the same sentence as CD4 in open-access papers (continued):
Sharing a sentence is not in itself a finding about the gene and the disease.
tumor (continued). "As for the result of dissecting distribution of tumor immune infiltrating cell types and correlation of age and these cells, age was negatively correlated with naive B cells and plasma cells while positively relevant to naive CD4+ T cells, M2 macrophages, resting mast cells and neutrophils." (PMID 35912097, 2022). "Thus, our data indicate that APR-246 stimulated a CD4+ T cell mediated anti-tumour immune response." (PMID 36138076, 2022). "However, it should be noted that cDC2s could also cross-present antigens and play a critical role for regulating anti-tumor CD4 and CD8 T cell responses." (PMID 35053338, 2022). "The frequencies of CD4+TNF-α+ and CD4+TNF-αhi negatively were associated with poor prognostic factors such as LN involvement (P = 0.015 and P = 0.019, respectively), stage of the disease (P = 0.032 and P = 0.010, respectively) and tumor size (P = 0.026 and P = 0.032, respectively)." (PMID 36376825, 2022). "The results suggest that the anti-tumor mechanism mediated by αCTLA-4 treatment in the IM vaccination may skew the neoantigen-specific immune response toward a CD8+IFNγ+ effector function whereas in the ID vaccination in the direction of CD4+TNFα+." (PMID 35110563, 2022). "The tumor antigens are then continuously presented to CD8+ and CD4+ T lymphocytes in the form of antigen peptide-MHC (p-MHC) molecular complexes to generate a large number of CTL and memory T cells, which can kill the tumor, reduce the risk of metastasis and prolong the survival time of patients." (PMID 35251013, 2022). "In addition, we followed-up the ICIs in blood: tumor-free and tumor-bearing animals which received LmAIO+α-PD-1 therapy demonstrated a predominantly low level of ICIs, whereas all other groups demonstrated elevated levels of ICIs on CD4/CD8 T cells." (PMID 35173308, 2022). "Taken together, this work sheds new light on the transcriptional regulation of the tumor marker Fascin by oncoproteins and identifies a cooperative effect of classical and alternative NF-κB activity to be crucial for induction of Fascin expression in CD4+ T-cells." (PMID 35158803, 2022). "As MHC-II is expressed by tumor cells in a large proportion of patients, and given the fact that when properly activated, CD4+ T-cells can kill MHC-II positive PDAC cells, we reasoned that MHC-II molecules on PDAC cells could be harnessed for neo-antigen-based immunotherapy." (PMID 35655709, 2022). "Along with monocyte chemotaxis to the tumor niche, HCMV-encoded IL-10, which appears to mimic the immunomodulatory effects of human IL-10, shifts monocyte polarization toward a deactivated pro-tumoral M2c phenotype, limiting CD4+ T cell activation and proliferation substantially." (PMID 35515137, 2022). "However, chemotherapy markedly reduced the proportion of T regulatory cells within the tumor and the ratio of CD4+ effector:CD4+ regulatory cells increased more than 2-fold from 1.6 to 3.4 (p = 0.029) whilst the CD8+:Treg ratio increased from 4 to 6.5 (p = 0.057)." (PMID 36253784, 2022). "Furthermore, TACE can act on the tumor microenvironment by decreasing the percentage of T-Reg and increasing the ratio of CD4+/CD8+, suggesting that TACE may interact with the antitumor activity of ICI." (PMID 36601120, 2022). "Furthermore, interrogation of the HIS in immune organs and tumors by flow cytometry revealed increased Granzyme B+, TNFα+ and IFNγ+ CD4+ T cells among the human tumor infiltrating leukocytes (TIL) that correlated with reduced tumor growth in the combination-treated HIS-mice." (PMID 36419897, 2022). "Interestingly, OX40 agonists used in tumor models increased mice survival and tumor-specific CD4 memory T cells in a cancer type- and anatomical site-dependent manner, suggesting that the context could significantly influence treatment efficiency." (PMID 34983927, 2022). "Thus, CD4+ T cell-based immunotherapy in combination with other therapies might represent an effective strategy to control tumor progression and recurrence." (PMID 35008422, 2022).
tumor (continued). "Next, we investigated whether activated tumor-specific CD4+ T cells could control solid tumors." (PMID 35784297, 2022). "However, isoform expression correlated with various clinical characteristics, including pathological stage, metastasis, cancer recurrence, and cancer infiltration by CD4+ T cells and CAFs in a limited number of tumour types where they predicted patients’ survival." (PMID 36498899, 2022). "Furthermore, C1 showed the lowest anti-tumor immune response, such as lower tumor infiltrating lymphocytes (naive B cell, CD 8 T cell, naive CD4 T cell) and stromal score and immune score, and these might be the causes of poor prognosis of subtype C1." (PMID 36119101, 2022). "In addition, considering our multivariate analysis suggesting a role for CD4+/FoxP3+ cells with PD-L1 expression, we postulate that this interaction might potentially play a central role towards tumor progression." (PMID 36268020, 2022). "Similarly, hepatocellular carcinoma patients with high levels of tumor‐infiltrating MAIT cells showed worse overall survival (OS) compared to those with low levels, and a regulatory subset of CD4+ MAIT cells was found to correlate with tumor bacterial load in human colorectal tumors." (PMID 35028137, 2022). "Thus, a deeper understanding of its regulation in CD4 T cell effectors at tumor sites may lead to improved immunotherapies and prognostic tools." (PMID 36358898, 2022). "Thus, our work further refines the phenotype of tumor-reactive CD4+ Th cells in human solid tumors." (PMID 35439168, 2022). "Therefore, the inhibition of tumor angiogenesis and vessel normalization by CD4+ T cells is likely an auxiliary mechanism that may be complemented by other antitumor functions of CD4+ T cells and other immune subsets." (PMID 36159781, 2022). "CD4+T cells can produce direct anti-tumour effects by secreting IFN-γ, We next detected the T cell ability in the spleen and draining lymph nodes to proliferate and secrete cytokines by flow cytometry to figure out whether LC4-PLG-RGD activates peripheral immunity." (PMID 36195696, 2022). "Thus, on the one hand, attenuated CD4+ T cell function could provide an immune-tolerant microenvironment, allowing cancer cells to evade anti-tumor responses." (PMID 35821823, 2022). "Although MS-275 could mobilize other lymphocytes with antitumor potential, selective depletion of CD4 or NK1.1-expressing cells during ACT+MS-275 treatment provided no loss of sustained tumor regression compared with CD8 depletion." (PMID 35972798, 2022). "Eomes may promote protective CD4 T cell activity by directly binding the regulatory regions of inhibitory molecules, thus lowering their expression on effector cells and increasing their effectiveness at tumor sites." (PMID 36358898, 2022). "Thus, cytotoxic CD4+ T cells may serve as a reservoir for the paracrine induction of HLA-II antigen presentation machinery in tumor cells." (PMID 35831288, 2022). "However, CD4+ T cells could be detected in every group of tumor tissues, and CD4+ T cells also play an essential role in inducing and stimulating tumor-specific CD8+ T cells." (PMID 36139670, 2022). "Thus, our results further confirmed the hypothesis that tumor antigen-specific CD4+ T cells are functionally activated by nsGO/PCP/OVA nanoparticle and exhibit strong humoral immune responses." (PMID 36727039, 2022). "CD4+ T cells may target cancer cells by modulating the tumor microenvironment." (PMID 35455287, 2022). "Therefore, it can be speculated that CD4+CD25+ Tregs in different tumor microenvironments are a potential mechanism of the heterologous effects of anti-PD-1 treatment." (PMID 35965575, 2022). "The high ratio of Foxp3+ Tregs to CD4+ effector Tcells in subcutaneous tumours may explain why they are refractory to PD-1 blockade.Conversely, the reduced fraction of Tregs in orthotopic tumours may explain theminimal response to CTLA-4 blockade." (PMID 35930804, 2022).
tumor (continued). "In addition to CD8 T cells, which directly recognize and kill tumor cells, we found that terminally exhausted PD-1hiCD39+ CD4 T cells at the tumor site are tumor-Ag-specific and lead to DC maturation and to Ag-specific CD8 T-cell proliferation following PD-1 blockade." (PMID 35954341, 2022). "Furthermore, using an autologous tumor lysate as a vaccine antigen was considered reliable against tumor development because it might consist of all the essential epitopes that could boost CD4+ assistant T cells and CD8+ T cells." (PMID 36298611, 2022). "Thus, despite CD8+ T cells were depleted, CD4+ T cells could mobilize the other immune cells to inhibit the growth of tumor." (PMID 35874660, 2022). "Finally, it will be essential to determine if the Tfh-like CD4 T cells can directly recognize tumor antigens in HNSCC patients, since this will directly relate to the specificity of B cells that they support and the CD8 T cells that they might help." (PMID 35937775, 2022). "illustrated that rosiglitazone in combination with gemcitabine could regulate T-cell populations by increasing circulating CD8+ T cells and intra-tumor CD4+ cells and CD8+ T cells, thereby reducing the progression and metastasis of pancreatic tumor, and further enhancing cell apoptosis." (PMID 36568247, 2022). "CD4+ VISTA+ T cell expression may correlate with tumor progression in NSCLC." (PMID 35122478, 2022). "Thus, we sought to evaluate the overall anti-tumoral status of the TIL infiltrates, assuming that CD8+ cells represent anti-tumor immunity while CD4+ cell subsets may contain significant fraction of Th2 T cells and therefore reflect pro-tumor characteristics." (PMID 35158957, 2022). "Thus, in the ‘preventative setting’, CD4+ T cells through IFNγ seem to be responsible for vessel fortification through pericyte recruitment consistent with previous studies of angiogenesis in early tumor development." (PMID 35712656, 2022). "In addition, the ratio of CD4+CD25+Foxp3+ cells was reduced to 56.5% in the tumor tissues of BALB/c mice inoculated with LN229 cells transfected with sh-lncRNA HOXA-AS2, while it was reduced to only 29.2% in tumor tissues of BALB/c mice inoculated with A172 cells transfected with sh-lncRNA HOXA-AS2." (PMID 35181676, 2022). "Besides, the NK cells may promote the formation and response of tumor-specific CD4+ and CD8+T cells." (PMID 36159787, 2022). "Furthermore, the study of tumour-infiltrating lymphocytes has become a hotspot, and tumour-associated macrophages (TAMs), CD8 + T cells and CD4 + T cells have effects on patient prognosis and are correlated with the efficacy of immunotherapy and chemotherapy in the clinic." (PMID 35248047, 2022). "Interferon-γ induces CD8+ T cells to antigen (Ag)-specific CTLs and CD4+ T cell differentiation, however, continuous exposure to interferon-γ may induce T cell exhaustion and tumor progression by inducing immune escape mediators, including PD-L1, STAT3, and IDO1." (PMID 36006412, 2022). "However, the importance of the tumour draining lymph nodes (TDLN) as the source of tumour-specific CD4+ and CD8+ cells and the site of important anticancer immunological events such as antigen presentation, immune cell activation, priming, proliferation and differentiation needs much more attention." (PMID 35714487, 2022). "Interestingly, analysis of tumor-infiltrating lymphocytes in the T cell reclustering analysis revealed that the number of CD4+ T cells and CD8+ T cells were increased significantly in the combination group compared with those in the control and single-use groups." (PMID 35260434, 2022). "Furthermore, the treatment could reduce primary 4T1 tumor progression and suppress abscopal metastasis via increasing M1 populations, as well as, enhancing CD4+ and CD8+ T cells infiltration in the distal tumor site." (PMID 37323705, 2022).
tumor (continued). "Using CRISPR/Cas9, we inactivated Stabilin-1, and found that its absence affected neither tumor size nor epithelial characteristics but was associated with a decrease in the intratumoral CD4+/CD8+ T-cell ratio, thereby supporting a potential immunosuppressive role for the STABILIN-1 macrophages." (PMID 36230610, 2022). "CD4+ T cells may be correlated with a favorable outcome due to their possible direct function as cytotoxic effectors, given the frequent MHC-I loss in this tumor." (PMID 35267668, 2022). "Interestingly, the results observed that 5 hub genes were shared in the GEO and TCGA profiles, including SLC44A3, DBF4, NAPSA, ATP6V0A4, and CLDN4, which were closely associated with B cells, CD4+ T cells, CD8+ T cells, Macrophage, Neutrophil, and Dendritic cells to involve in tumor immunity." (PMID 36325324, 2022). "It should be noted that due to the expression of CD3+ in CD4+ and CD8+ T cells, the action of TCEs in the tumor site would not be restricted to CD8+ T cells, and the expected activation of CD4+ T cells might also contribute to the outcome of the immune response against the tumor." (PMID 36678761, 2022). "As such, they could present tumor antigens to CD4+ TH cells by Class II HLA molecules." (PMID 35593340, 2022). "However, further characterization of CD4 phenotypes in tumor-bearing and tumor-naïve mice could yield insight into the impact of SHP2 inhibition on immune exhaustion." (PMID 36969745, 2022). "However, the PD-1highCD25-Foxp3+CD4 Tregs had minimal proliferation as assessed by Ki67 expression, suggesting Treg conversion and inhibition of Treg tumor egress rather than proliferation as the causes of accumulation in TILs." (PMID 35449134, 2022). "As the helper cells, decreased naïve CD4+/CD4+ percentages and increased CD4+ T cell counts, memory CD4+/CD4+ percentages might suggest that the anti-tumor immune response was activated and naïve CD4+ T cells were differentiated into CD4+ T cells and memory CD4+ T cells." (PMID 34488711, 2021). "Various populations and subpopulations of lymphocytes, such as cytotoxic T lymphocytes (CD8+), helper T lymphocytes (CD4+), and B lymphocytes, along with other types of immune cells, such as NK cells, acting in the tumor microenvironment may exert coordinated or sometimes even contrary responses." (PMID 34692375, 2021). "Our results indicated that cryo-thermal therapy could inhibit tumor metastasis and improve long-term survival, induce the differentiation of CD4+ T cells toward a Th1 polarizing phenotype, downregulate the proportion and suppressive function of Tregs and drive the fragility of Tregs." (PMID 34576115, 2021). "Notably, administration of A. muciniphila to microbiota-depleted mice with fecal transplantation from nonresponders stimulated Il-12-dependent infiltration of Ccr-9+ Cxcr-3+ Cd4 + T cells into tumor beds, resulting in the restoration of the anticancer effect of PD-1 blockade." (PMID 33435800, 2021). "Tumor progression may be caused by Th1/Th2 mixed reaction or Th2 dominant response, relying on TGF-β and IL-10 to transform Th1 cells into Th2 cells to reverse the anti-tumor effects of CD8+ cytotoxic T cells and CD4+ Th1 cells, which is thought to be a tumor immune escape mechanism." (PMID 34625124, 2021). "Moreover, we described how the TME could reprogram tumor reactive CD4+ T cells epigenetic landscape and modulate their functionality and recruitment at tumor site by regulating the expression of immune inflammatory cytokines and attracting chemokines." (PMID 34262562, 2021). "There is increasing evidence that immune cell infiltration can influence tumor progression and recurrence and become an important determinant of immunotherapeutic response and clinical outcome.CD4+ T cells recognize cancer antigens, while macrophages may be involved in tumor inhibition." (PMID 34794429, 2021).
tumor (continued). "Furthermore, when the immune parameters were correlated to the SGR, we did observe the tumor size as a function of the immune response, e.g. smaller tumors appeared to be enriched in CD4+HLA-DR+ T cells in HIS-CRC-BRGS mice treated with combination immunotherapy." (PMID 33854497, 2021). "Thus, significant enrichment of macrophages M1 activated CD4 memory T cells in the tumor microenvironment and that of the hallmark IL6/JAK/STAT3 signaling pathway in tumor tissues indicate initiation, growth, and escape of OSCC-GB tumor cells from host immune response." (PMID 33980865, 2021). "Furthermore, agents such as cyclophosphamide have been shown to deplete tumour-infiltrating Treg numbers and their suppressive function in mouse models, as demonstrated by a significantly decreased expansion of CD4+/CD8+ T-cells in the presence of untreated Tregs." (PMID 34944851, 2021). "Additionally, the mean SpatialScore was significantly different from that of a random sample in responders, but not in nonresponders, suggesting that an active process specifically coordinates the spatial interactions of PD-1+ CD4+ T cells, tumor cells, and Tregs in responders." (PMID 34795254, 2021). "YTHDC2 expression is significantly correlated with B cells, CD4+T cells, neutrophils, and dendritic cells, but not with macrophage infiltration in HNSCC, indicating that YTHDC2 may play an important role in immune cells in the tumor microenvironment, especially CD4+T cells and dendritic cells." (PMID 34136491, 2021). "However, depletion of CD4+T cells marginally affected the efficacy, suggesting that inhibition of tumor growth by CYH33 may be predominantly dependent on CD8+T cells." (PMID 34373258, 2021). "Finally, as the fundamental role of anti-tumour CD4+ T cell responses becomes increasingly apparent, one under-explored area that should be examined would be the dynamics of the interaction between CD4+ T cells and myeloid-derived suppressor cells (MDSCs) within the tumour microenvironment." (PMID 32457487, 2021). "However, a major role for human CD4+ T cells in PC3 tumor control in NSG mice has been reported." (PMID 34208480, 2021). "Therefore, the infiltration of naïve B cell, Plasma cells, resting CD4 memory T cell in the tumor microenvironment may be harmful to patient prognosis." (PMID 34332535, 2021). "Cbx3/HP1γ deficiency in CD4+ T cells did not enhance tumor cells killing." (PMID 34721405, 2021). "To further identify their correlations with infiltrating immune cells, we explored in TISIDB dataset and found that TICRR was associated with activated CD4 T cell and PPIF was correlated with CD56dim natural killer cell, implying that immunocytes may play an essential role in tumor microenvironment." (PMID 33495413, 2021). "However, we found that neoadjuvant chemotherapy could only slightly promote the infiltration of immune cells in the overall tumor area, among which the infiltration of CD4+ GzmB+ T cells were significantly increased in NCT group." (PMID 34631551, 2021). "To study whether TBI alters the migration properties of adoptively transferred CD4+ T cells in a non tumor-bearing host, we applied 107 DID-fluorescently labeled Tag-Th1 cells i.p. to C3H mice 24 h after TBI in accordance with our established T cell-based immunotherapy of RIP1-Tag2 mice." (PMID 34335959, 2021). "Modulation of myeloid cells may be superior to other strategies in clinical development aimed at depleting myeloid cells since the early modulation of myeloid cells preceded the sustained infiltration of CD8+ and CD4+ T lymphocytes, which was essential for anti-tumour efficacy." (PMID 33531689, 2021). "Understanding these mechanisms of antigen priming and/or re-stimulation within the specific tumour microenvironments would be critical to harness the full potential of CD4+ T cells in cancer immunotherapy, and may inform rational combinations with therapies targeting antigen-presenting cells." (PMID 32457487, 2021).